CTNNB1 (catenin beta 1)
Diseases named in the same sentence as CTNNB1 in open-access papers (continued):
Sharing a sentence is not in itself a finding about the gene and the disease.
cancer (continued). "Atypical endometrial hyperplasia/EIN and EC shares several molecular alterations with each other, including microsatellite instability, PAX2 inactivation, mutation of PTEN, KRAS, and CTNNB1 (β-catenin), but there is not a linear accumulation of mutational events leading to cancer." (PMID 31293968, 2019). "Indeed, we speculate that the selectivity for Nutlin‐3a in CTNNB1‐mutant cancer cells is cancer type‐specific." (PMID 29532999, 2018). "The low mutation prevalences, especially among those with diagnoses of regional or distant disease, suggest that somatic mutations in CDH1 and CTNNB1 are unlikely to explain a substantial proportion of cancer cell detachment from primary carcinomas originating at most anatomic sites." (PMID 29156750, 2017). "However, together with further experimental validation, we may conclude that anticancer drugs that inhibit the expression of CTNNB1 might be useful in treating APC mutant cancers." (PMID 26937901, 2016). "Mantel-Cox log rank test showed that patients with CTNNB1 mutated cancers had a reduced survival compared to not-mutated, suggesting a correlation between CTNNB1 mutations and poor prognosis (P = 0.036; Mantel-Haenszel hazard ratio [HR] 3.73; 95% confidence intervals [CI]." (PMID 27276713, 2016). "For instance, while most CRCs harbor APC mutations, a subset of CRCs and other cancers lacking APC mutations have CTNNB1 gene mutations resulting in production of oncogenic β-catenin proteins that are resistant to regulation by the destruction complex and that activate β-catenin/TCF transcription." (PMID 26528816, 2015). "Based on this analysis, the genes STAT3, MYC, CTNNB1, ESR1, JUN, and BRCA1 emerged as pivotal genes, indicating their significant impact on each cancer type in response to radiation exposure." (PMID 41186627, 2025). "ClueGO analysis indicated that 16 of the 48 DEPs were directly related to 17 pathways, with CTNNB1 and CDH1 involved in eight pathways related to cell adhesion and junction formation and seven cancer-related KEGG pathways, respectively." (PMID 40150405, 2025). "Through both the targeting of CTNNB1 mRNA and the regulation of a plethora of miRNAs, KSRP has the potential to be a more appreciated contributor to canonical Wnt regulation in many cancers." (PMID 41516083, 2025). "Cancer cells are defined as cells expressing high MKI67, CAV1, and CTNNB1 and present spatial variations in the expression of VEGFC, FN1, and NRP1." (PMID 40081369, 2025). "Several other cancer-related alterations were detected at lower frequencies, including alterations in PTEN, PIK3CA, APC, and CTNNB1 genes." (PMID 40699829, 2025). "Bioinformatics analysis indicated that CTNNB1 and CDH1 are involved in placental development and pregnancy maintenance via cell adhesion and junction processes as well as cancer-related pathways." (PMID 40150405, 2025). "Bioinformatic analysis of Kyoto Encyclopedia of Genes pathways suggested that CTNNB1 and CDH1 are involved in cell adhesion and cancer, with implications for placental development." (PMID 40150405, 2025).
cancer (continued). "We performed a head-to-head comparison of N-acetylgalactosamine (GalNAc)-conjugated small interfering RNA (siRNA)-mediated inhibition of five genes (CDK1, PD-L1, CTNNB1, SMYD3, ANLN) to prevent cancer in four distinct autochthonous HCC mouse models." (PMID 40704506, 2025). "In contrast, immune inhibitory genes in cancer cells, e.g., ENPP1, CTNNB1, PRMT5, were depleted after lymphocyte-cancer co-culture." (PMID 38678024, 2024). "In CRC, the expression of JUN was reported to be upregulated and play an important role in the cancer progression by making a complex with the TCF4 and β‐catenin (CTNNB1) transcription factors." (PMID 38872418, 2024). "In this Chinese PDAC cohort, KRAS mutations were mutually exclusive with P/LP alterations in BRAF, CTNNB1, ELF3, FGF19, and other cancer‐related genes." (PMID 36999792, 2023). "By the way, an average proportion of GAs for known oncogenes (e.g., KIT, MYC, CTNNB1, MDM2 and APC) in the same pan-cancer cohort ranges from four to 9%." (PMID 37373333, 2023). "Last, we correlated CTNNB1 and TNF expression in the AMs of patients with cancer, highlighting the translational relevance of our findings." (PMID 37092550, 2023). "We observed an upregulation of CTNNB1 and other genes involved in CTNNB1 stabilization (CSNK2A1, CSNK2B, DVL2, DVL3,) in rHGP cancer areas." (PMID 36691028, 2023). "We observed a transient increase in CTNNB1 and a sustained increase in CD44, a cancer stem cell marker downstream of CTNNB124,25." (PMID 35906361, 2022). "Kyoto encyclopedia of genes and genomes (KEGG) analysis showed that hsa_circ_0004099 was enriched in several cancer pathways, which were collectively enriched in four genes namely TCF7L2, NRAS, CTNNB1, and KRAS." (PMID 36399471, 2022). "In this section, we discuss how mushrooms help overcome multidrug resistance (MDR) and target signaling pathways, such as PI3K/AKT, Wnt-CTNNB1, and MAPK, during cancer treatment." (PMID 36142412, 2022). "A total of five cancer-related genes (BDNF, PTGS2, CTNNB1, GSK3B, and HPGD) were selected based on the Gene Ontology database." (PMID 35054980, 2022). "ESR1 deems to share CTNNB1-54 and AKT1-55 mediated signalling pathways to accelerate cancer and neurodegeneration, respectively." (PMID 36229517, 2022). "The genes selected included epithelial (KRT5, CDH1, EpCAM), mensenchymal (VIM, SNAI1, TWIST), stem (ALDH1A1, PROM1), breast specific (ESR1, PALB2) and other genes related to cell cycle or other cancer pathways (CCND1, CTNNB1, Ki67, etc.)." (PMID 34071445, 2021). "Aberrant expression of CTNNB1 and WNT5A has been observed to affect cell proliferation and lead to cancer occurrence." (PMID 34249080, 2021). "The repression of miR-181 by CRNDE determined the higher expression of CTNNB1 and transcription factor 4 (TCF4) miR targets with a promotion of cancer cell growth, 5-FU and L-OHP resistance in CRC cells." (PMID 34503164, 2021). "We found that the target gene CTNNB1 of ENSCHIG00000000641 is one of the two signaling pathway members of Wnt and proteoglycans in cancer." (PMID 34249080, 2021).
cancer (continued). "With 10 identifiers, we observed that these genes interacted with stemness genes such as SOX-2 and NANOG, genes important in cancer pathways such as STAT3, CTNNB1, EGFR, TNF, and CASP3, and immune genes such as IL2 and CD4." (PMID 34685742, 2021). "In bone-related cancer cell lines, ASPH has significant correlations with GSK3B (Pearson r = 0.50, p = 0.01) and CTNNB1 (Pearson r = 0.54, p = 0)." (PMID 33015050, 2020). "We also see CTNNB1, KLF4, HIF1A, and MYC as particularly important across many cancers as well as evidence to suggest substantial cross-talk and perhaps overlap." (PMID 33106165, 2020). "CTNNB1 plays an important role in the Wnt/β-catenin pathway and contributes to EMT in multiple cancers." (PMID 32211242, 2020). "Anoikis resistance has been reported to be caused by abnormal expression of certain genes (such as TrkB, CTNNB1 and HSP70A1A) or pathways (such as the Wnt/β-catenin pathway), and enhance the metastatic ability of cancer cells 29, 36-38." (PMID 32685004, 2020). "Pathways related to nervous system development (FDR = 5.8 × 10−8) were enriched for the PID-N genes ASCL1, CTNNB1, ID2, SUFU, and TERT that have known roles in cancer, complementing the PID-C genes NOTCH1, PTEN, and RHOA that also have known cancer roles." (PMID 32024854, 2020). "High expression of the putative cancer and hematopoietic stem cell marker THY1/CD90 and WNT11 and CTNNB1 also suggest potential novel therapeutic strategies to increase pCR rates." (PMID 30967156, 2019). "Recently, RuvB-like 2 (RUVBL2) was found to interact with catenin beta 1 (CTNNB1), telomerase reverse transcriptase (TERT), MYC proto-oncogene (MYC), nuclear factor-kappa B1 (NFKB1), etc. to regulate the cancer-related signaling pathways in HCC." (PMID 31572066, 2019). "To find a possible link between these three cancers subjected to arsenicals exposure, we merged the three networks and identified seven HUB nodes (RXRA, MAP3K7, NR3C1, PABPC1, NDRG1, RELA and CTNNB1) of the linking region between three cancer networks." (PMID 29991691, 2018). "In summary, our current study showed that DAW22 inhibited both sporadic and NF1‐related MPNST cancer cell proliferation and induced apoptosis by targeting AKT, ERK, and CTNNB1 pathways." (PMID 30112810, 2018). "Our analysis show that younger patient cancers with Gleason score equal 8 and 9 are characterized by significant overexpression both of CDH1 and CTNNB1." (PMID 29206234, 2017). "Among these, the mRNA levels of PIK3R1 and CTNNB1 were increased more than 2-fold, and those of PIK3R3, PIK3CA and AKT3 were increased 1.6- to 1.9-fold after co-culture with cancer cells." (PMID 28173828, 2017). "Various cancer-related genes were also differentially expressed significantly, including BRAF, BRCA2, VEGFA, VEGFB, RET, PIK3CA, CTNNB1 and GNAS." (PMID 27350898, 2016). "These zones also show parallel alternating levels and/or subcellular localization of multiple cancer stem/progenitor cell (CSC) markers, including β-catenin/CTNNB1, ALDH1, and CD44." (PMID 26098881, 2015). "In the spleen, 8/84 cancer-related genes were affected in FLT mice compared to AEM controls (P<0.05; up: Cdkn2a; down: Birc5, Casp8, Ctnnb1, Map2k1, Mdm2, NFkB1, Pdgfa)." (PMID 24069384, 2013).
cancer (continued). "There was also a concomitant decrease (2.5 fold) in mRNA transcript of CTNNB1 and other elements of Wnt/β-catenin signaling (e.g. axin, DVL1, GSK3β) in cancer cells compared to normal cells." (PMID 20454608, 2010). "• Exertion of anticancer effects through 3 major pathways: apoptosis (BIRC3, BIRC5, caspase-8, caspase-9, and PARP1), transcriptional dysregulation in cancer (CDKN1A, CDKN1B, MMP9, MYC, JUN, and RELA), and cancer progression (caspase-3, CCND1, CTNNB1, VEGFA, and Wnt-1)." (PMID 39181121, 2025). "And we have determined LINC02418 could exert its cancer-promoting effects by interacting with YBX1 and enhancing YBX1 DNA-binding ability to the CTNNB1 promoter, which could induce the transcription of β-catenin and result in the activation of Wnt pathway." (PMID 40082414, 2025). "In 2 BCA cases, PD56517a and PD52408a, both the recurrent CTNNB1 and FBXW11 mutations were absent, as were mutations in other Wnt signalling pathway genes and COSMIC Cancer Gene Census genes." (PMID 40389436, 2025). "In the 235 extracranial solid tumors with histologies not included in prior pediatric pan-cancer analyses, the recurrently altered genes uniquely containing oncogenic alterations (compared to the common tumors) were CTNNB1, DICER1, and NF1." (PMID 38992034, 2024). "In the 78 CNS tumors with histologies not included in prior pediatric pan-cancer analyses, the recurrently altered genes uniquely containing oncogenic alterations (compared to the common tumors) were CTNNB1, NF2 and KIT." (PMID 38992034, 2024). "This gene set contained well-known cancer driver genes ARID1A, PTEN, PIK3CA, and CTNNB1." (PMID 37444632, 2023). "CTNNB1 and ZNRF3 were the most prevalent altered cancer-related genes." (PMID 38023213, 2023). "We then explored by real-time qPCR the impact of miR-662 overexpression in MDA-MB-231 cells on expression levels of well-established stemness markers that are involved in embryogenesis and cancer –NOTCH1, WNT7b, ZEB1, TCF3, CTNNB1, CD44, CD24, SNAI2, OCT-04, c-MYC, EZH2–." (PMID 37443350, 2023). "Other critical nodes include AKT1, SRC, CTNNB1 and EGFR, which are related to cancer signalling." (PMID 36944690, 2023). "Upregulation of CTNNB1 and CCND1 may also increase cancer cell invasion, according to certain reports." (PMID 36708238, 2023). "However, GSK3B (Glycogen Synthase Kinase 3 Beta) acts as a negative regulator in the phosphorylation of key cancer-related genes, such as APC, JUN, and CTNNB1/beta-catenin." (PMID 35645340, 2022). "Furthermore, these cancer pathways were jointly enriched in four genes, TCF7L2, NRAS, CTNNB1, and KRAS, which are mainly involved in cell proliferation." (PMID 36399471, 2022). "Finally, by considering the genes recapitulating IL-3 biological functions, we proposed a model, including IL-3Rα, SNAI1, ZEB1, VIM, CTNNB1, MMP2, SPRY2, and CD274, that remarkably discriminates cancer aggressiveness (AUC = 0.86 95% CI = 0.82–0.89)." (PMID 36010912, 2022).
cancer (continued). "Since TWIST1 and β-catenin both play important role in cancer formation and progression, we hypothesized that TWIST1 may regulate β-catenin expression and function due to the correlation of TWIST1 and CTNNB1 in our EMT assay." (PMID 36123378, 2022). "CTNNB1, KRAS, and NRAS are also three intersecting genes in the cancer pathway in this study, indicating that they may be key target genes regulating the development of AIS." (PMID 36399471, 2022). "Moreover, the transcription factor CUX1, by targeting key subunits of the Wnt/β-Catenin pathway, showed a positive correlation with mRNA expression of Axin2, CTNNB1, and TCF4 in most normal and cancer tissues or cell lines." (PMID 34422906, 2021). "The three clusters generated contained genes or proteins involved in apoptosis (BIRC3, BIRC5, PARP1, CASP8, and CASP9), transcriptional dysregulation in cancer (CDKN1B, RELA, CDKN1A, MYC, JUN, and MMP9), and cancer progression (CCND1, CASP3, CTNNB1, WNT1, and VEGFA) pathways." (PMID 34836311, 2021). "Furthermore, Spearman correlation analysis in TCGA HCC tissues revealed that MARCH6 was positively correlated with MKI67, CTNNB1, CDH2, FN1 and WNTSA, which were demonstrated as oncogene in cancer growth and metastasis." (PMID 34273954, 2021). "After birth, WNT/CTNNB1 responsive stem cells are responsible for tissue homeostasis in various organs and hyperactive WNT/CTNNB1 signaling is observed in many different human cancers." (PMID 32083079, 2020). "The previous analytic results together with these reports indicated that hsa_circ_0088494-miR-876-3p might influence CTNNB1 and CCND1 expression and function, thereby exerting their roles in mediating cancer carcinogenesis and progression." (PMID 33363164, 2020). "SIGLEC family genes were further associated with specific oncogene mutation in different cancer types and were differentially expressed between patients of mutation and non-mutation groups, such as APC in COAD and READ, or CTNNB1 in LIHC." (PMID 33240817, 2020). "Furthermore, mutations were detected in genes that are known for their involvement in other cancer types, such as TERT, KMT2D, PIK3CA, AKT1, CTNNB1 and NR1D1." (PMID 32455687, 2020). "Our study contributes molecular clues by indicating that this is not linked to CTNNB1/ARID1A mutations, but more likely attributed to the hypoxia frequently found in cancers." (PMID 33084574, 2020). "The intertwined relationship of CTNNB1, GSK3, and TrCP1 could be a novel and interesting area for cancer therapeutic development." (PMID 31699039, 2019). "As AKT, ERK, and CTNNB1 are currently the most important components in the transduction pathways for MPNST disease progression, DAW22 can be used as a potential therapeutic alternative in fighting against cancer, especially in AKT‐resistant cancer types." (PMID 30112810, 2018). "Furthermore, the expression of SLC2A1, CTNNB1, ACTB, and CLTC were significantly changed in only one type of cancer during migration." (PMID 28640862, 2017). "Another 6 genes, SUB1, SLC2A1, CTNNB1, ACTB, HSP90B1, and CLTC were selected from the remaining unknown migration-related genes in order to confirm their relationship with cancer cell migration." (PMID 28640862, 2017).